FKTN (fukutin)
Description:
Catalyzes the transfer of a ribitol-phosphate from CDP-ribitol to the distal N-acetylgalactosamine of the phosphorylated O-mannosyl trisaccharide (N-acetylgalactosamine-beta-3-N-acetylglucosamine-beta-4-(phosphate-6-)mannose), a carbohydrate structure present in alpha-dystroglycan (DAG1). This constitutes the first step in the formation of the ribitol 5-phosphate tandem repeat which links the phosphorylated O-mannosyl trisaccharide to the ligand binding moiety composed of repeats of 3-xylosyl-alpha-1,3-glucuronic acid-beta-1. Required for normal location of POMGNT1 in Golgi membranes, and for normal POMGNT1 activity. May interact with and reinforce a large complex encompassing the outside and inside of muscle membranes. Could be involved in brain development (Probable).
Synonyms: FCMD; LGMD2M; CMD1X; LGMDR13; MDDGA4; MDDGB4; MDDGC4
Tractability: Antibody: UniProt predicts a signal peptide or a membrane-spanning region.
Gene: Protein-coding gene on chromosome 9 (105,558,122 to 105,653,820, forward strand). Ensembl gene ENSG00000106692.
Subcellular location: Golgi apparatus membrane; Cytoplasm; Nucleus
Pathways (Reactome):
Metabolism of proteins: Matriglycan biosynthesis on DAG1
Gene Ontology:
Molecular function: phosphotransferase activity, for other substituted phosphate groups; protein binding
Biological process: negative regulation of cell population proliferation; negative regulation of JNK cascade; protein O-linked glycosylation; protein O-linked glycosylation via mannose; glycoprotein biosynthetic process; muscle organ development; nervous system development
Cellular component: catalytic complex; cis-Golgi network; endoplasmic reticulum; Golgi apparatus; Golgi membrane; nucleus; cytoplasm; extracellular region
Genetic constraint (gnomAD): Loss-of-function variants: 20 observed, 28.43 expected, observed/expected ratio (o/e) 0.7, 90% interval 0.49 to 1.02. The upper end of that interval is the gene's LOEUF score, 1.02, which puts it in group 4 of 6, group 1 being the genes least tolerant of losing a copy. Missense variants: 278 observed, 283.87 expected, observed/expected ratio (o/e) 0.98, 90% interval 0.89 to 1.08. Synonymous variants: 91 observed, 106.21 expected, observed/expected ratio (o/e) 0.86, 90% interval 0.72 to 1.02.
Gene-disease validity (ClinGen):
ClinGen rates the evidence that FKTN causes each of these diseases.
myopathy caused by variation in FKTN (autosomal recessive): Definitive. Any myopathy in which the cause of the disease is a variation in the FKTN gene.
Homologues: Orthologues: chimpanzee FKTN (99% identical), macaque FKTN (98% identical), pig FKTN (93% identical), dog FKTN (93% identical), guinea pig FKTN (89% identical), mouse Fktn (89% identical), rat Fktn (89% identical), rabbit FKTN (88% identical), tropical clawed frog fktn (63% identical), zebrafish fktn (55% identical), Caenorhabditis elegans T07D3.4 (22% identical), Caenorhabditis elegans Y22D7AL.11 (21% identical), and 3 more.
Diseases named in the same sentence as FKTN in open-access papers:
FKTN is named in the same sentence as 55 diseases in open-access papers, as found by Europe PMC text mining. Sharing a sentence is not in itself a finding about the gene and the disease. The quoted sentences say what the papers report.
dystroglycanopathy (29 papers, 2013 to 2025). "The use of rapamycin also has been explored as a treatment for LGMDM2, dystroglycanopathies caused by mutations in FKTN." (PMID 37892218, 2023). "In another study, disrupting the interaction between αDG and laminin was found to induce apoptosis and reduce Akt phosphorylation while treatment of a fukutin-deficient dystroglycanopathy with the mTOR inhibitor RAPA was found to increase myofiber size." (PMID 36878377, 2023). "Of note, there are already some patients described with compound heterozygous or homozygous FKTN variants and a limb–girdle dystrophy–dystroglycanopathy." (PMID 37834164, 2023). "Inhibition of mTORC1 by rapamycin improves muscle pathology in the fukutin-deficient mouse model of dystroglycanopathy and the mdx mouse model of Duchenne muscular dystrophy." (PMID 37021539, 2023). "It is known that mutations in FKTN affect the glycosylation of α-dystroglycan, leading to a dystroglycanopathy." (PMID 35743126, 2022). "Within dystroglycanopathies clinical spectrum, FKTN mutations are causative of 3 distinct phenotypes, which differ in clinical severity and CNS involvement." (PMID 31756055, 2020). "To date, mutations in at least 15 genes, including FKTN, encoding fukutin, have been identified as causative for secondary dystroglycanopathies." (PMID 27257474, 2016). "In a mouse model of fukutin-deficient dystroglycanopathy, all antibodies detected low molecular weight alpha-dystroglycan in disease samples demonstrating a loss of functional glycosylation." (PMID 24824861, 2014). "To generate double mutant mice, we crossed dysferlin-deficient SJL/L mice (dysferlinsjl/sjl) with two distinct dystroglycanopathy models, fukutin-deficient or Large-deficient mice." (PMID 25198651, 2014). "Although FKTN is associated with dystroglycanopathy usually in the context of homozygous or compound heterozygous variants, the enrichment of heterozygous regulatory variants in our cohort may suggest a contributory role for this gene in CMP." (PMID 35288587, 2022). "Mutations in FKTN-encoding fukutin, a Golgi-based ribitol phosphate transferase, might cause α-dystroglycanopathy in combination with cardiomyopathy." (PMID 35743126, 2022). "Moreover, reporting on a new mutation and a putative functional effect can be valuable in understanding pathogenic mechanisms involving FKTN and performing genotype–phenotype correlations in the dystroglycanopathies phenotype spectrum." (PMID 31756055, 2020). "To investigate contributions of dysferlin deficiency to the pathology of dystroglycanopathy, we have crossed dysferlin-deficient dysferlinsjl/sjl mice to the fukutin-knock-in fukutinHp/− and Large-deficient Largemyd/myd mice, which are phenotypically distinct models of dystroglycanopathy." (PMID 25198651, 2014). "Furthermore, Golgi dysfunction in dystroglycanopathy was hypothesised as a contributing factor for the heterogeneity of these disorders in Fukutin-deficient mouse cardiac cells." (PMID 34012031, 2021). "Whilst there has been no previous detailed quantitative assessment of muscle development in secondary dystroglycanopathy mice, other work has suggested that the severity of the phenotype may correlate with when the expression of genes, such as that encoding for fukutin, are deleted." (PMID 26900448, 2016). "FKRP gene mutations have also been involved in α-Dystroglycanopathies together with PMOT1 (LGMDR11), FKTN (LGMDR13), PMOT2 (LGMDR14), and POMGNT1 (LGMDR15) gene mutations." (PMID 41009401, 2025). "Due to the enrichment of regulatory variants in FKTN and DTNA, we expanded our search to additional dystroglycanopathy genes (LARGE1, POMT1, POMT2) and identified two regulatory variants of interest in LARGE1 in gene-elusive cases." (PMID 35288587, 2022). "Our analysis shows that several myopathogenes associated with secondary or tertiary dystroglycanopathies (POMT1, FKTN, POGLUT1, POMK, POMGNT2, ISPD and B4GAT1) are downregulated during satellite cell activation." (PMID 34740639, 2022).
dystroglycanopathy (continued). "Another candidate experimental therapy – overexpression of the LARGE enzyme – has been shown to restore αDG function in a variety of α-dystroglycanopathies caused by mutations in FKRP, FKTN, POMGNT1 and POMT1." (PMID 32423971, 2020). "Very similar brain involvement was found in WWS patients with genetically confirmed dystroglycanopathy due to mutations in other genes like POMT2, LARGE, POMGnT1 and FUKUTIN, respectively." (PMID 31311558, 2019). "Similar results have previously been reported in dystroglycanopathy patients with Protein-O-mannosyl transferase 1 (POMT1), Protein-O-mannosyl transferase 2 (POMT2), POMGnT1, FKTN and FKRP mutations." (PMID 30553274, 2018). "We initially aimed to elucidate the pathogenesis of brain abnormalities in dystroglycanopathies using mice with brain-selective conditional knockout of fukutin (fukutin-cKO mice) as a model." (PMID 29360985, 2018). "Fukutin is the first dystroglycanopathy gene identified for FCMD, which is among the most common autosomal recessive disorders in Japan." (PMID 29360985, 2018). "Therefore, future research in a larger cohort is needed to elucidate the potentially beneficial effects of this supplement in dystroglycanopathy patients with an FKRP, FKTN, or ISPD mutation." (PMID 38736632, 2024). "Similarly, fukutin mutation compromises the glycosylation of DAG1, leading to Fukuyama congenital muscular dystrophy, a milder dystroglycanopathy characterized by progressive muscle weakness and brain vessel dysfunction." (PMID 36463265, 2022). "To date, at least 18 genes, including fukutin, fukutin-related protein (FKRP), isoprenoid synthase domain-containing protein (ISPD), and like-acetylglucosaminyltransferase (LARGE), have been identified as causative genes for dystroglycanopathy." (PMID 29360985, 2018). "In addition to fukutin-cKO mouse strains, we further evaluated two mouse models of dystroglycanopathy." (PMID 29360985, 2018). "Mutations in ISPD, FKTN and FKRP lead to dystroglycanopathies with severe neuromuscular symptoms." (PMID 27194101, 2016). "Although it has been reported that several dystroglycanopathy models with mutations in POMGnT1, LARGE, or fukutin could be recovered by LARGE overexpression, laminin-binding glycans were not rescued by LARGE overexpression in AGO-deficient MEFs." (PMID 24256719, 2013). "Among these, POMT1, POMT2, POMGnT, FCMD, Fukutin, and LARGE genes are reported to code for specific or putative glycosyl-transferases involved in the pathway of alpha-dystroglycanopathies." (PMID 27576556, 2016). "However, no causative treatment is yet available for ISPD, FKTN, and FKRP‐related dystroglycanopathies." (PMID 38736632, 2024). "Among dystroglycanopathies, good correlation between α-DG staining and disease course was demonstrated in only a few forms (POMT1, POMT2, and POMGnT1-mutated cases), and is absent in patients with mutations in FKRP and FKTN." (PMID 26404900, 2015).
muscular dystrophy (17 papers, 2010 to 2025). Muscular dystrophy (MD) refers to a group of more than 30 genetic diseases characterized by progressive weakness and degeneration of the skeletal muscles that control movement. "Congenital muscular dystrophies linked to fukutin and fukutin-related proteins constitute two distinct subgroups of dystroglycanopathies, for which comprehensive analyses of proteasomal activity and autophagic flux have been carried out." (PMID 40422224, 2025). "Mutations in glycosylating enzymes, such as Fukutin and Large, cause muscular dystrophies of different severities and times of onset." (PMID 35990309, 2022). "To date, αDG O-mannose glycosylation disorders have been linked to mutations in more than a dozen genes, including FKTN (fukutin), establishing a prevalent family of autosomal recessive muscular dystrophies." (PMID 24824861, 2014). "Point mutations in fukutin have been reported in patients both inside and outside Japan, and recent studies have revealed a broad clinical spectrum for fukutin-deficient muscular dystrophies." (PMID 25198651, 2014). "In this study, we reported the case of a patient with muscular dystrophy, early onset dilated cardiomyopathy, and elevated creatine kinase levels who was a carrier of the compound heterozygous variants p.Ser299Arg and p.Asn442Ser in FKTN." (PMID 35743126, 2022). "FKTN is associated with the rare muscular dystrophy, Fukuyama-type muscular dystrophy." (PMID 32013268, 2020). "In this study, we reported the case of a male patient diagnosed with muscular dystrophy, DCM (heart transplanted at the age of 19 years), and elevated CK levels, who is the carrier of two FKTN missense variants." (PMID 35743126, 2022). "Hence, the generation of fukutin conditional knockout rats is deemed crucial for advancing research aimed at addressing muscular dystrophy." (PMID 38785502, 2024). "MCK-Fukutin-cKO mice exhibit milder phenotype of muscular dystrophy than mdx and Largemyd/myd mice." (PMID 35990309, 2022). "This FKTN-genotype was recently identified in another German patient with muscular dystrophy." (PMID 35743126, 2022). "Next, sgRNA with optimal targeting activity was selected by performing PCR analysis and the T7E1 assay, and the CRISPR/Cas9 system was used to construct a rat model for muscular dystrophy by inducing a deficiency in the fukutin gene without any off-target effect detected." (PMID 38785502, 2024). "Muscular dystrophy is not observed in a mouse model of Fukuyama congenital muscular dystrophy, which occurs due to a retrotransposition insertion in the mouse fukutin ortholog and leads to laminin binding at 50% of normal levels." (PMID 36723429, 2023). "However, some studies demonstrate that FKTN, POMT1, and DAG1 are involved in muscular dystrophy." (PMID 29949603, 2018). "We previously generated knock-in mice carrying a founder retrotransposal insertion in fukutin, the gene responsible for FCMD, but these mice did not develop muscular dystrophy, which hindered exploring therapeutic strategies." (PMID 25198651, 2014).
Fukuyama congenital muscular dystrophy (12 papers, 2011 to 2025). "This highlights that fukutin variants, beyond causing Fukuyama congenital muscular dystrophy, can underlie LGMD phenotypes with dystroglycanopathy-related cardiomyopathy." (PMID 40870035, 2025). "Fukuyama congenital muscular dystrophy [OMIM:253800] is a rare AR CDG originating from mutations in the fukutin (FKTN) gene located on chromosome 9q31.2." (PMID 37239976, 2023). "Pathogenic FKTN variants are associated with different phenotypes, for example, the severe Fukuyama congenital muscular dystrophy (FCMD)." (PMID 37834164, 2023). "The causative gene of Fukuyama congenital muscular dystrophy (fukutin) is involved in formation of the basement membrane through glycosylation of alpha-dystroglycan." (PMID 34830034, 2021). "We recently demonstrated that fukutin, the gene responsible for Fukuyama congenital muscular dystrophy, encodes the ribitol-phosphate transferase essential for dystroglycan function." (PMID 29360985, 2018). "Similarly, a 3.1-kb SVA insertion in the Fukutin (FKTN) gene has been described as causative in Fukuyama-type congenital muscular dystrophy (FCMD) (OMIM #607440, #253800)." (PMID 41155689, 2025). "Finally, FKTN mutations are commonly associated with Fukuyama congenital muscular dystrophy in Japan, which is characterised by hypotonia, muscle weakness, and cerebral and cerebellar cortical dysplasia." (PMID 30060766, 2018). "We examined transcripts encompassing the CDSs for M-RAS, encoding a muscle-specific RAS protein; the myosin heavy chain protein MYH4, which is primarily expressed in skeletal muscles; and fukutin (FKTN), the locus for Fukuyama congenital muscular dystrophy." (PMID 21232131, 2011).
congenital muscular dystrophy (9 papers, 2015 to 2025). A muscular dystrophy that is characterized by diminished muscle tone (hypotonia), progressive muscle weakness and degeneration (atrophy), abnormally fixed joints, spinal rigidity, and delays in reaching motor milestones such as sitting or standing unassisted. "Exon-skipping therapy is an approved treatment for Duchenne muscular dystrophy and recently, we developed a therapeutic strategy using branchpoint-targeted antisense oligonucleotides for patients with Fukuyama congenital muscular dystrophy caused by an FKTN transcript involving a pseudoexon." (PMID 39755676, 2025). "Mutations in the gene for fukutin, FKTN, and subsequent aberrant glycosylation of α-dystroglycan are responsible for dilated CM and several forms of congenital muscular dystrophy, such as LGMD2M." (PMID 34298968, 2021). "The expert consortium suspected alpha-dystroglycan-related congenital muscular dystrophy, including Fukuyama type, and fukutin gene analysis was performed." (PMID 30894207, 2019).
cardiomyopathy (5 papers, 2018 to 2024). A disease of the heart muscle or myocardium proper. "Our work showed that compound heterozygous mutations in FKTN lead to a loss of fully glycosylated α-dystroglycan and result in cardiomyopathy and end-stage heart failure at a young age." (PMID 35743126, 2022). "In our study, we showed that compound heterozygous mutations in FKTN led to cardiomyopathy, resulting in early end-stage heart failure with persisting elevated CK levels, even after HTx." (PMID 35743126, 2022). "Consequently, our work showed that compound heterozygous mutations in FKTN lead to a loss of fully glycosylated α-dystroglycan and result in cardiomyopathy and end-stage heart failure at a young age." (PMID 35743126, 2022). "This variant in FKTN, associated with both HCM and DCM, is likely a Qatari/Arabic founder mutation leading to cardiomyopathy in both the heterozygous and homozygous state." (PMID 34137518, 2021).
dilated cardiomyopathy (4 papers, 2011 to 2026). Cardiomyopathy which is characterized by dilation and contractile dysfunction of the left and right ventricles. "Patients with dilated cardiomyopathy and no or minimal muscle involvement were reported with mutations in fukutin (FKTN,) and fukutin-related protein (FKRP,), showing reduced laminin binding capacity of alpha-dystroglycan in heart muscle biopsies." (PMID 22242004, 2011).
gastric cancer (4 papers, 2021 to 2022). A primary or metastatic malignant neoplasm involving the stomach. "An upregulation at the mRNA or protein level of the gene encoding fukutin (FKTN) has been found to be related to the tissue of origin or the progression of tumors in patients with stomach cancer." (PMID 36494657, 2022). "A study of gastric cancer indicated that higher FKTN expression is associated with tumor progression, which may be due to the protein encoded by FKTN promoting the interaction between tumor cells and the extracellular matrix." (PMID 35047511, 2021). "FKTN expression was correlated with carcinogenesis and may be a key regulator of intestinal gastric cancer progression." (PMID 36605944, 2022). "On the other hand, the FKTN mRNA was found upregulated in the stomach cancer cell lines MKN-1 and MKN-45, and at the protein level additionally in the HSC-57 cell line, which was consistent with the overexpression also reported in samples from patients with stomach cancer." (PMID 36494657, 2022). "It has been reported that the expression level of fukutin varies among different histological types and grades of gastric cancer; in particular, fukutin expression in gastric carcinomas arising in atomic bomb survivors was more upregulated in the high-radioactivity-exposure group." (PMID 34830034, 2021).
astrocytoma (2 papers, 2021 to 2022). "Our observations of the fukutin knockdown-driven decreases in cell proliferation ability and cyclin D1 expression level in 1321N1 cells highlight that fukutin enables astrocytoma cells to proliferate." (PMID 34830034, 2021). "By contrast, a role of fukutin in the nucleus to activate cell proliferation has been reported in the 1321N1 astrocytoma cell line, this suggesting that fukutin could act in a different fashion depending on the cell type." (PMID 36494657, 2022). "In the present study, we convincingly demonstrated the presence of fukutin protein in the nucleus, as well as the cytoplasm, of astrocytoma-derived 1321N1 cells, evidenced by immunocytochemistry on chamber slides and Western blotting of nuclear and cytoplasmic fractions." (PMID 34830034, 2021).